IER2 (immediate early response 2)
Diseases named in the same sentence as IER2 in open-access papers (continued):
Sharing a sentence is not in itself a finding about the gene and the disease.
tumor (17 papers, 2016 to 2025). "Further spatial transcriptomic (ST) data from six tumor samples indicated a significant spatial co‐expression between IER2 and HIF‐1α." (PMID 39207055, 2024). "Clinically, a significant correlation of high IER2/ITGB1 expression with tumor aggressive phenotype and poor patient survival is observed." (PMID 39207055, 2024). "We found that IER2+ ERS‐CAF density was significantly correlated with the invasive tumor phenotype (such as AJCC staging, high pathological grade, and invasion of surrounding muscle) and poor patient clinical outcomes." (PMID 39207055, 2024). "To analyze the association of IER family members (IER2, IER5 and IER5L) with tumor pathogenesis and progression, we interrogated public transcriptomics datasets containing gene expression data from different tumor types using Cancertool." (PMID 39025841, 2024). "Remarkably, however, the top hit among the differentially expressed genes between H3.3K27M tumor cells and normal brain cells is immediate early response protein 2 (IER2), a suppressor of neuronal differentiation upon JNK-dependent induction." (PMID 31175278, 2019). "In addition, we also conducted transcriptomic sequencing on ten regions of interest (ROIs, each containing both tumor and stromal cells) with high (n = 5) or low (n = 5) stromal IER2 expression using GeoMx Digital Spatial Profiler (DSP) method." (PMID 39207055, 2024). "Human immediate early response 2 (IER2) is a nuclear protein that is implicated in cancer via transcriptional regulation of endothelial motility and adhesion via a FAK-dependent mechanism, thereby regulating tumor angiogenesis." (PMID 36033825, 2022). "To date, however, the association between IER2 expression and tumor progression has not been explained mechanistically, in particular the consequence of the constitutive rather than transient expression that is observed in many cancers." (PMID 34611309, 2021). "In addition, by analyzing the bulk RNA‐seq data, we unveiled that high expression of IER2 was positively correlated with high pathological grade, tumor invasion of surrounding muscle tissues, advanced AJCC staging as well as poor overall survival and local recurrence‐free survival of patients." (PMID 39207055, 2024). "Conversely, the genes downregulated in the MYB-expressing epithelial clusters were predominantly tumor-suppressive transcriptional signatures, including OCM, IER2, JPH2, RYR3, MYH11and B3GALT1." (PMID 40950184, 2025). "Noticeably, our analysis also disclosed that IER2+ ERS‐CAF displayed the most proximity to ITGB1+ tumor cells, mainly enriched within a 60 μm radius of ITGB1+ tumor cells." (PMID 39207055, 2024). "A comparison of EGR1, FOS, IER2, JUN, KLF6, MYC, and FOSL2 gene expression in 481 tumor samples revealed that individual tumors vary substantially in the expression of all analyzed genes." (PMID 39436655, 2024). "Given CAFs' genetic uniformity and lower drug resistance compared to tumor cells, these findings may lay the foundation for developing future therapeutic strategies by targeting ERS‐CAF through interventions with IER2 blockade or ERS inhibitors." (PMID 39207055, 2024). "IER2 also induces expression of ERS‐CAF marker genes and results in production of a pro‐tumorigenic paracrine GMFG signaling, which exert its biological function via directly binding to ITGB1 on tumor cells." (PMID 39207055, 2024). "Both populations displayed striking transcriptional divergence following chemotherapy exposure with 906 and 817 DEGs within the COL1A2 and IER2 populations respectively, whilst the MFAP5 fibroblasts showed highest transcriptional difference in tumor vs normal comparisons." (PMID 36253784, 2022). "Two fibroblast subpopulations, characterized by high level expression of COL1A2 and IER2, were markedly increased within the tumor microenvironment and almost completely absent in adjacent normal esophageal tissue." (PMID 36253784, 2022).
tumor (continued). "Unchanged Rb (retinoblastoma) phosphorylation and protein levels, together with unaffected p16INK4a (p16) levels indicate that IER2-mediated senescence is independent of the tumor-suppressor p16-Rb pathway." (PMID 34611309, 2021). "Interestingly, both IER2 and IER5 reportedly contribute to tumor progression." (PMID 39025841, 2024). "Unlike IER2 and IER5, the role of IER5L has been poorly studied and thus, we lack basic understanding of the possible contribution of IER5L to tumor progression and metastasis." (PMID 39025841, 2024). "The expressions of all module genes were significantly discrepant by comparing normal samples with tumor, including three genes (ATF3, IER2, and NNR4A2) downregulated in para‐cancerous compared to normal tissues, which were also low expressed in BC compared to normal samples." (PMID 35037412, 2022). "Furthermore, the IER2-induced SASP in the senescent subpopulation of cells could conceivably stimulate the growth and aggressiveness of non-senescent tumor cells." (PMID 34611309, 2021).
cancer (8 papers, 2021 to 2025). A tumor composed of atypical neoplastic, often pleomorphic cells that invade other tissues. "Expression of the immediate-early response gene IER2 has been associated with the progression of several types of cancer, but its functional role is poorly understood." (PMID 34611309, 2021). "Compared to RWPE-1, cancer cells showed stronger H3K27ac signals, and MIR1204, IER2, SMAD3, and FOXA1 were SE-associated in PC-3 and DU145 but not RWPE-1." (PMID 41330917, 2025). "Likewise, IER2 has been proposed to participate in tumorigenic processes such as cell motility and adhesion, angiogenesis, invasion and metastasis in several cancer types, including colorectal and hepatocellular carcinoma." (PMID 39025841, 2024). "Interestingly, we found that the TAM1 and TAM3 cells also show high expression levels of multiple oncogenes, such as DUSP1, IER2 and NAMPT, which have been implicated in cancer progression." (PMID 34805184, 2021). "In total, 41 and 65 differentially enriched genes were identified from CUT&Tag and ChIP-seq data, respectively, with only FOXA1 and IER2 appearing in both datasets, highlighting FOXA1 as a conserved, cancer-specific SE target." (PMID 41330917, 2025). "IER5L is a member of the IER family that shares homology at its N-terminal domain with IER2 and IER5, which reportedly contribute to different aspects of cancer biology." (PMID 39025841, 2024). "To identify other components of the IER2-induced SASP, we next employed a broader panel of 84 key genes involved in cancer inflammation and immunity." (PMID 34611309, 2021). "IER5L levels consistently increased across cancer types (with a similar non-significant trend in PCa), while IER2 expression was largely reduced, and IER5 exhibited inconsistent alterations." (PMID 39025841, 2024). "This module included a number of immediate early and growth factor response genes and overlapped with modules previously identified for SDF1 responses in PBs (genes such as CD69 and NR4A2) and growth factor responses in cancer (genes such as EGR1/3, FOS, FOSB, and IER2)." (PMID 36130130, 2022). "IER2-induced OPN expression mediates these effects and can act in a paracrine manner on neighboring, non-senescent cancer cells." (PMID 34611309, 2021). "Unlike IER2 and IER5, the role of IER5L in cancer aggressiveness has been poorly studied." (PMID 39025841, 2024).
infection (2 papers, 2017 to 2024). The state of being infected such as from the introduction of a foreign agent such as serum, vaccine, antigenic substance or organism. "C1ORF159 and IER2 levels change comparably upon infection in wild-type HeLa and BBC3as knockout cells, as measured by RT-qPCR and Nanostring nCounter assays." (PMID 29089033, 2017). "IER2 is known to be upregulated in response to external stimuli including infection." (PMID 38720891, 2024). "Similarly to IER2, the pro-apoptotic gene ING1 was induced by MAP kinases as well, and, like IER2, showed higher mRNA levels at all timepoints after infection compared to uninfected cells under PAA treatment." (PMID 29089033, 2017). "IER2 is induced by the MAP kinase pathway, which is in turn activated by the infection itself." (PMID 29089033, 2017).
IER2 also shares sentences with these, for which no sentence is quoted: hepatocellular carcinoma (2 papers); breast adenocarcinoma (1); depression (1); non-small cell lung carcinoma (1); osteosarcoma (1); prostate carcinoma (1); skin cutaneous melanoma (1).